STAT1 (signal transducer and activator of transcription 1)
Diseases named in the same sentence as STAT1 in open-access papers (continued):
Sharing a sentence is not in itself a finding about the gene and the disease.
Autoimmunity (continued). "Both FOXP3 and RORγt were undetectable in three patients with IL2RG, RAG1 and STAT1 mutations, implying that Treg and Th17 cells were almost completely absent, and therefore they had increased risks of developing autoimmune disorders and opportunistic infections." (PMID 32670274, 2020). "Gain-of-function mutations of STAT3 cause early-onset lymphoproliferative disease and autoimmunity, those of STAT1 lead to chronic mucocutaneous candidiasis, but also autoimmunity, and dominant negative mutations of STAT3 cause a hyper-IgE syndrome, known as Job syndrome." (PMID 31443172, 2019). "Moreover, it was discovered that mice with a deficiency of miR-146a develop a late autoimmunity caused by an impaired activation of NF-κB in T cells, and signal transducer and STAT1 activator in regulatory T cells." (PMID 30646527, 2019). "Thus, it is unclear whether abnormal responses to pathogenic microbes promote autoimmunity in STAT1 GOF patients with T385M and other DBD mutations." (PMID 37275873, 2023). "However, the underlying molecular and cellular mechanisms of autoimmunity in STAT1 GOF patients are unknown." (PMID 37275873, 2023). "In addition to compromising Th17 differentiation, STAT1 GOF may also promote the differentiation of effector CD4 lineages linked to autoimmunity." (PMID 37275873, 2023). "Thus, we propose that monocytes (and DCs) contribute to the pathogenesis of STAT1 GOF-associated autoimmunity, which may be at least partly driven by the TLR7/8 hyperresponsiveness to self-nucleic acids." (PMID 36172362, 2022). "Hence, our findings suggest that IL-6-induced STAT1 may promote early events that govern the transition into pathogenic T cells driving autoimmunity." (PMID 35911690, 2022). "Although, so far, there is no clear genotype-phenotype correlation, considering the varying gain-of-function effect of STAT1 variants, it would be interesting to evaluate whether autoimmunity associates with STAT1 variants resulting in stronger interferon signaling." (PMID 33795850, 2021). "Extensive research has confirmed the pathological roles of the IL-6/JAK2/STAT1/3 signaling pathway in inflammation, autoimmunity, and cancer, as well as its involvement in the pathogenesis of various rheumatic diseases." (PMID 40170729, 2025). "As reported by Strøm, one of our patients adds a new form of autoimmunity to STAT1 GOF, namely autoimmune hypertriglyceridemia due to GPIHBP1 autoantibodies." (PMID 40881691, 2025). "We suspect that the STAT1 change was maternally inherited and expressed in an autosomal dominant pattern given the proband’s mother’s history of autoimmunity and possible onychomycosis." (PMID 40704637, 2025). "Investigation of the possible sex effect of autoimmunity in human STAT1 DBD GOF is therefore warranted, including assessment of the types of autoimmune manifestation, age of onset and severity." (PMID 37275873, 2023). "Foxp3+ T-regulatory (Treg) cells are another key subset in autoimmunity that range from low-normal in STAT1 GOF patients." (PMID 37275873, 2023). "A balanced equilibrium of STAT1 signaling is central to avoid severe and possibly life-threatening infections, because STAT1 GOF typically leads to autoimmunity and CMC." (PMID 37140667, 2023). "Alterations in DNA methylation and MBD2 expression can influence the maintenance of Th1 program homeostasis, via the binding of MBD2 to methylated CpG DNA within the Stat1 promoter, thereby preventing autoimmunity." (PMID 37742034, 2023). "Signal transducer and activator of transcription 1 (STAT1) gain-of-function (GOF) is an autosomal dominant immune disorder marked by wide infectious predisposition, autoimmunity, vascular disease, and malignancy." (PMID 33990617, 2021). "A specific single-nucleotide polymorphism in STAT1, rs1467199, plays a potential role in IFN-γ dependent autoimmunity in pediatric ITP." (PMID 33552061, 2020).
Autoimmunity (continued). "Increased activity of STAT1, as a result of impaired nuclear de-phosphorylation, is proposed to lead to autoimmunity by increasing IFN alpha signalling." (PMID 30888520, 2019). "We screened all participants for the seven genes known to cause monogenic autoimmunity that can include diabetes (AIRE, IL2RA, FOXP3, LRBA, STAT1, STAT3, STAT5B)." (PMID 29417186, 2018). "As patients with STAT1 gain-of-function (GOF) mutations also develop CMC and autoimmunity, we focused on the STAT1 node, which is involved in the type I IFN system in antiviral defense, development of mTECs, and maintenance of thymic architecture." (PMID 30002654, 2018). "Patients with STAT1 gain-of-function (GOF) mutations also develop CMC and autoimmunity; they exhibit increased STAT1 protein levels at baseline and STAT1 phosphorylation (pSTAT1) upon interferon (IFN)-γ stimulation relative to healthy controls." (PMID 28769929, 2017). "Another signaling pathway relevant to autoimmunity is the Jak-stat pathway that is represented in our dataset by the upregulation of STAT1 and STAT5b." (PMID 28441778, 2017). "In addition to NF-κB and STAT1 activation, we discovered mTOR pathway activation, shedding new light on A20’s function and progression toward autoimmunity." (PMID 40719110, 2025). "Cells from STAT1 GOF patients typically show elevated pSTAT1 (Tyr701) levels after stimulation with IFNs, suggesting that autoimmunity could be linked to IFN hyper-responsiveness." (PMID 37275873, 2023). "Many autoimmune disorders are more prevalent in females due to a variety of IFN-dependent and -independent mechanisms, so sex may also modulate autoimmunity in STAT1 GOF these patients." (PMID 37275873, 2023). "Finally, the JAK1/2 inhibitor ruxolitinib, which blocks the JAK kinase upstream from STATs, has been successfully used to ameliorate CMC and autoimmunity in several STAT1 GOF patients." (PMID 37358695, 2023). "Our data provide evidence that defective IFN-γ/STAT1 signaling may increase endogenous antigen presentation with the potential for enhancing autoimmunity and impaired protective immunity against exogenous pathogens." (PMID 36445781, 2023). "As patients with STAT1 GOF and type I interferonopathies show overlapping clinical features in autoimmunity, predisposition to IFN-related autoimmunity seems plausible and might need to be taken into account when deciding for personalized therapy." (PMID 37140667, 2023). "Having found increased PNAs in the STAT1 GOF patients, we suggest that they may constitute another relevant driver of the STAT1 GOF autoimmunity." (PMID 37358695, 2023). "However, the reduced activity of Th1 cells came at the expense of provoking a more significant pathogenic role of Th17 cells within an inflammatory setting, leaving STAT1 a controversial target for preventing overt autoimmunity." (PMID 36591260, 2022). "In this study, both mTORC1 and STAT1 signalling were enhanced in CCR2‐deficient mice, promoting B‐cell metabolism and transcriptional signalling, thus suggesting the role of this mechanism in autoimmunity." (PMID 35875970, 2022). "Although several hypotheses have been suggested, such as aberrant functions of regulatory T cells, B cells, and the upregulated type I IFN signaling, the molecular mechanism behind autoimmunity in STAT1 GOF patients remains unexplained." (PMID 36172362, 2022). "In summary, the dataset presented here indicates a proinflammatory skew and abnormal functions of STAT1 GOF monocytes of patients with CMC, which may directly contribute to both their microbial susceptibility and autoimmunity." (PMID 36172362, 2022). "Therefore, our study suggests that the STAT1 pathway can be manipulated to limit autoreactive T cells during autoimmunity directed against the CNS." (PMID 35587373, 2022).
Autoimmunity (continued). "It is noteworthy that autoimmune disorders seem to be more common in STAT1 GOF than in STAT1 LOF; such conditions involve the endocrine system, Thyroid disease was the most common, indicating that thyroid function and autoantibodies should be examined routinely in patients with STAT1 GOF mutations." (PMID 33777053, 2021). "Loss-of-function mutations of JAK3 are associated with severe combined immune deficiency (SCID); similarly, loss-of-function mutations of STAT1 and STAT2 were also found responsible for immunodeficiency, whereas STAT5 deficiency can lead to both immunodeficiency and autoimmunity." (PMID 31443172, 2019). "Patients with STAT1 GOF mutations also develop CMC and autoimmunity." (PMID 30002654, 2018). "Our results also suggest that IL-27 may promote autoimmunity toward pancreatic islets via the upregulation of the STAT1 pathway." (PMID 28248954, 2017). "Therefore, it is not surprising that the biological and clinical features observed, such as autoimmunity, inflammation, elevated IgE, eosinophilia, and recurrent infections, overlap with those reported in patients carrying GOF variants in STAT1, STAT5, or STAT6." (PMID 41136770, 2025). "Similarly, heightened Stat1 activation in Tregs subjected to a selective ablation of SOCS1, a key negative regulator of Stat1 phosphorylation downstream of the IFN-γ receptor, was associated with analogous Th1-mediated pathology-associated autoimmunity." (PMID 31273052, 2019). "Among them, STAT1 and STAT4 are directly involved in interferon and cytokine signaling, which are central to APS-related inflammation and autoimmunity." (PMID 40429780, 2025). "Most STAT1-GOF patients, particularly those who had autoimmunity, presented increased IGS that significantly decreased in the two patients during ruxolitinib treatment." (PMID 38578354, 2024). "STAT1-GOF patients exhibited increased ISG, compared to healthy subjects, that was augmented in patients with autoimmunity." (PMID 38578354, 2024). "The clinical picture of STAT1 GOF exemplifies how the seemingly paradoxical coexistence of immunodeficiency and autoimmunity is reality for many patients." (PMID 37140667, 2023). "This simplistic understanding is outdated and instead a new way of thinking about STAT1, STAT3, STAT6, JAK1, and JAK3 LOF and GOF disease in terms of the relationship between immunodeficiency and autoimmunity is developing." (PMID 37140667, 2023). "This STAT1 overactivation, as it also occurs for example in recombinant IFN-α therapy as a phenocopy of STAT1 GOF, seems to be involved in the pathogenesis of autoimmunity." (PMID 37140667, 2023). "Together, our findings suggest that MBD2 directly binds to the methylated CpG DNA within the Stat1 promoter to suppress its transcriptional activity, thereby maintaining the homeostasis of the Th1 program in CD4 T cells to prevent organ-specific autoimmunity." (PMID 34420035, 2022). "Our study further reveals that transcriptional regulators such as IRF3, IRF7, STAT1, and MYB are critically involved in T cell-mediated autoimmunity, along with ncRNAs LINC00487, LINC01260, and MIR223 with their expression patterns linked to immune dysregulation." (PMID 39844998, 2025). "AD STAT5b deficiency: growth-failure and eczema without immune defects; (iii) AD STAT1 GOF CMC and autoimmunity; (iv) AR ITCH deficiency: autoimmunity, dysmorphic facial features and neurodevelopmental delay." (PMID 39945219, 2025). "STAT1-GOF disease is characterized by infections and autoimmunity." (PMID 41142635, 2025). "When compared to CVID patients without autoimmunizations, up-regulation of STAT1 and IRF1 gene expression was observed." (PMID 38474381, 2024). "Surprisingly, novel therapies, like JAK1/2 inhibitors, showed not only the potency to suppress the enhanced STAT1 phosphorylation in CD4+ T lymphocytes but may also improve clinical outcome in both immunodeficiency and autoimmunity features." (PMID 28348565, 2017).
Autoimmunity (continued). "However, environmental and molecular mechanisms contributing to autoimmunity in STAT1 GOF patients are not defined." (PMID 37275873, 2023). "Therefore, we hypothesized that monocytes might represent important co-orchestrators of antifungal defense failure, as well as various immunodysregulatory phenomena seen in patients with STAT1 GOF CMC, including autoimmunity." (PMID 36172362, 2022). "The regulatory mechanism that BCL6 could be transactivated by STAT1 was also observed in imatinib-treated chronic myeloid leukemia cells and contributed to CD4+ T follicular helper cell TFH differentiation and autoimmunity." (PMID 35503721, 2022). "JAK inhibitors such as ruxolitinib have been shown to reduce STAT1 hyperphosphorylation in STAT1 GOF patients, ameliorating not only the CMCC but also symptoms of autoimmunity." (PMID 40704637, 2025). "In contrast, studies of humans or other mouse models with STAT1 GOF did not report sex effects on development of immune abnormalities and autoimmunity." (PMID 37275873, 2023).
colon carcinoma (62 papers, 2008 to 2026). "In the present study, we attempted to examine the expression of immune surface markers in colon cancer cells and elucidate the mechanisms underlying the effects of STAT1 on immune surface markers." (PMID 34758826, 2021). "IF staining of WT colon tumour tissue indicated STAT1 activation in IECs during AOM-DSS treatment, and confirmed the STAT1 activation deficiency in Casp11−/− colon tumours." (PMID 30538296, 2019). "Recent studies have implicated STAT1 in tumor–stroma interactions, and its expression and activity are perturbed during colon cancer." (PMID 30235866, 2018). "Collectively, this data adds to existing understanding of the mechanism underlying cytokine regulation of MMP expression via STAT-1, and increases our understanding of the links between inflammation and malignancy in colon cancer." (PMID 28819304, 2017). "Myeloid cells from colon carcinoma-bearing mice exhibit elevated iNOS and NO, which is associated with increased levels of nitration on STAT1, resulting in suppression of the anti-tumor immune response." (PMID 26497740, 2015). "We compared the ability of human intestinal fibroblasts isolated from normal mucosa (HIF ND) and myofibroblasts isolated from a patient with UC or CD, risk factors for colon cancer, to activate STAT1 in colonic epithelial cells." (PMID 24818101, 2014). "In this study, we established that normal intestinal fibroblasts activate STAT1 signaling in colon cancer cells and, in contrast to cancer-associated fibroblasts, inhibit growth of tumor cells." (PMID 24818101, 2014). "An increase in STAT1 expression and activation in human ulcerative colitis (UC) was reported, and UC patients are at higher risk of colon cancer." (PMID 23724058, 2013). "Furthermore, active KRAS mutations in colon cancer cells were shown to inhibit the expression of STAT1, allowing them to escape tumor surveillance mechanisms due to reduced responsiveness to IFN-γ." (PMID 30235866, 2018). "Since KRAS and BRAF gene mutations are frequently present in colon cancers and have adverse prognostic significance, we examined whether mutations in these genes were more prevalent in tumors with high STAT1 expression, which could have contributed to poor prognosis." (PMID 32275681, 2020). "In colon cancer patients, the expression levels of STAT1, IRF2 and PDCD1 are positively correlated in tumor-infiltrating myeloid cells." (PMID 38995014, 2024). "In human colon cancer patients, the expression levels of STAT1, IRF2 and PDCD1 are positively correlated in tumor-infiltrating myeloid cells." (PMID 38995014, 2024). "In contrast, in a mouse model of colitis-associated cancer and cells from colon cancer patients, it was demonstrated that TIM-3 promotes the development of tumor-supporting M2 macrophages via a STAT1-dependent pathway." (PMID 37928435, 2023). "The reduction of MMP-1 and MMP-3 expression was reported to correlate with the inflammatory cytokine IL-6, signal transducer and activator of transcription (STAT), and the AP-1 (IL-6/STAT-1/AP-1) axis in colon cancer." (PMID 36839884, 2023). "STAT1 binds to the IRF promoter region in colon cancer cells, while MBD1 inhibits IRF8 expression, which is another indication evidence that WT1 in leukemia and IRF8 are anticorrelated." (PMID 37250717, 2023). "Upon fludarabine treatment, decreased STAT1 mRNA levels in both murine colon cancer cells were observed, and more importantly, the stimulated expression of IFI35 by IFNγ was attenuated." (PMID 37380972, 2023). "In fact, a specific depletion of STAT1 has been described in various malignant cell lines including human lymphocytes, natural killer cells, breast, colon carcinoma, and neuroblastoma upon F-araA treatment." (PMID 33300108, 2021). "It has been reported that in in human KRAS-G12D colon tumor cells, STAT1 can act in a cell-autonomous manner to promote tumor growth, which indicated that inhibition of STAT1 will suppress the KRAS-G12D colon tumor growth." (PMID 34578339, 2021).